ATP1A2 (ATPase Na+/K+ transporting subunit alpha 2)
Diseases named in the same sentence as ATP1A2 in open-access papers (continued):
Sharing a sentence is not in itself a finding about the gene and the disease.
migraine (continued). "Some ATP1A2 mutations have been shown to be associated with non-hemiplegic migraine phenotypes, such as basilar migraine and the common migraine." (PMID 23561701, 2013). "Intriguingly, mutations in ATP1A2 have also been shown to be associated with non-hemiplegic migraine phenotypes, such as basilar migraine and even common migraine, although this causality has not been definitively confirmed." (PMID 22940869, 2012). "The CACNA1A and ATP1A2 genes have both previously been tested in the common forms of migraine, but no new mutations or the FHM mutations were detected in these MA/MO affected samples." (PMID 16162291, 2005). "About 10% of ATP1A2 mutations were identified in migraine with or without aura (MA/MO) indicating that the gene might also be a susceptibility locus for common forms of migraine." (PMID 27445835, 2016). "Our analyses of the ATP1A2 gene demonstrated one polymorphism that was nominally associated with ischemic stroke; however this association did not persist with correction for multiple testing, nor was this association mediated by migraine status." (PMID 23459313, 2013). "While we did identify one ATP1A2 polymorphism, rs2070704, that may play a role in early-onset stroke pathogenesis, particularly among African-Americans, migraine did not mediate this affect." (PMID 23459313, 2013). "While our results do not demonstrate a strong relationship between ATP1A2 polymorphisms and migraine associated stroke risk, the results are hypothesis generating and indicate that an association between ATP1A2 polymorphisms and stroke risk may exist." (PMID 23459313, 2013). "We did not observe an association between ATP1A2 polymorphisms and migraine." (PMID 23459313, 2013). "Interestingly, ATP1A2 mutations associated with non-hemiplegic migraine phenotypes, such as basilar migraine and even common migraine have been reported." (PMID 21731499, 2011). "A recent biocomputational genetic association analysis of migraine and RA demonstrated that there is a phylogenetic relationship between the genes responsible for migraine and RA, such as SLC24A3 and HLA-B, MPPED2 and STAT4, and ATP1A2 and IL6R, respectively." (PMID 35281991, 2021). "Familial hemiplegic migraine (FHM) is a rare, monogenic, autosomal dominant subtype of migraine, in which three genes, CACNA1A, ATP1A2, and SCN1A, are currently known to be involved." (PMID 30498473, 2018). "Our patients who had ATP1A2 or SCN1A mutations also showed recurrent ataxia, vertigo/dizziness, and interictal nystagmus without hemiplegic migraine." (PMID 29062094, 2017). "Yet, although ATP1A2 is a key player in K+ clearance, this aspect has been considered less important for the pathophysiology of migraine because the duration of the CSD was not prolonged in the FHM2 mouse model." (PMID 27445835, 2016). "Psychotic symptoms during the aura of hemiplegic migraine have been described in few cases with FHM1, in a sporadic case linked to ATP1A2 gene mutation, and in a few cases without genetic investigation." (PMID 22661290, 2012). "Molecular analysis of the CACNA1A and ATP1A2 genes in patients with migraine without aura and with aura, has shown that these two genes are not involved in common forms of migraine, although similar studies have not examined the SCN1A gene." (PMID 21713554, 2011). "Until now, three undisputed hemiplegic migraine genes, CACNA1A (FHM1), ATP1A2 (FHM2), SCN1A (FHM3), have been identified; despite recent technical advances in whole genome/whole exon next generation sequencing no additional hemiplegic migraine genes have been identified." (PMID 34112082, 2021).
familial hemiplegic migraine (67 papers, 2010 to 2026). A migraine disorder characterized by individual and family history of aura that includes motor weakness. "One illustrative example is familial hemiplegic migraine caused by mutations in the ATP1A2 gene that encodes the predominant Na+-K+ ATPase in astrocytes." (PMID 38405021, 2024). "ATP1A2 mutation is generally associated with familial hemiplegic migraine and polymicrogyria in the brain." (PMID 35751846, 2022). "Previously, we reported a novel ATP1A2 mutation, G762S, that caused pure familial hemiplegic migraine, which inspired us to study the functional properties of FHM with different neurological symptoms." (PMID 34384358, 2021). "In fact, ATP1A2 represents one of the known susceptibility loci of familial hemiplegic migraine in humans." (PMID 30154697, 2018). "It has similar clinical characteristics as familial hemiplegic migraine, where several mutations in the ATP1A2 gene have been found to be pathogenetic." (PMID 24396618, 2013). "A more recent case study featuring a male adolescent who was diagnosed with familial hemiplegic migraine (FHM2) revealed a heterozygous genetic mutation within the ATP1A2 gene (c.1133C > T); this missense mutation may inhibit the function of the α2 subunit of the Na+/K+ ATPase." (PMID 38731230, 2024). "Mutations in the ATP1A2 gene generally occur in familial hemiplegic migraine (FHM, familial hemiplegic migraine)." (PMID 35751846, 2022). "Genetic factors play a significant role, with mutations in genes like CACNA1A, ATP1A2, and SCN1A implicated in familial hemiplegic migraine, a rare subtype, and potentially contributing to broader aura susceptibility through ion channel dysfunction." (PMID 40873917, 2025). "The genetic basis for CSD is supported by its strong association with familial hemiplegic migraine (FHM), where mutations in genes, such as CACNA1A, ATP1A2, and SCN1A, alter ion channel function, predisposing the brain to hyperexcitability." (PMID 40869402, 2025). "HM is categorised based on family history, with familial hemiplegic migraine (FHM) linked to pathogenic variants in the CACNA1A, ATP1A2, and SCN1A ion transport genes." (PMID 40725463, 2025). "Genetic studies have identified several mutations associated with familial hemiplegic migraine, including CACNA1A (FHM1), ATP1A2 (FHM2), and SCN1A (FHM3)." (PMID 41552155, 2025). "Familial hemiplegic migraine (FHM), an autosomal dominant hereditary form of HM, is linked to mutations in specific genes (CACNA1A, ATP1A2, SCN1A) that encode ion channels and transporters critical for neuronal excitability and synaptic transmission." (PMID 40264646, 2025). "The transmission of three genes linked to ion transport, CACNA1A, ATP1A2, and SCN1A, is responsible for the onset of familial hemiplegic migraine." (PMID 35328439, 2022). "Pathogenic variants in ATP1A2 are more commonly associated with familial hemiplegic migraine (FHM)." (PMID 33794876, 2021). "Mutations in the ion transport genes CACNA1A, ATP1A2 and SCN1A can lead to familial hemiplegic migraine, indicating genetic heterogeneity." (PMID 34384358, 2021). "The calcium channel gene, CACNA1A, has been identified as a key gene in which mutations can cause familial hemiplegic migraine (FHM), along with several other FHM-related ion channel genes (ATP1A2, SCN1A)." (PMID 32233732, 2020). "Familial hemiplegic migraine (FHM), which is a subtype of migraine with aura, is caused by mutations in CACNA1A, ATP1A2, and SCN1A." (PMID 33193064, 2020). "Interestingly, a mutation in ATPase Na+/K+ transporting subunit α 2 (ATP1A2), previously associated with familial hemiplegic migraine (FHM), was reported in a 24-year old male with IPAH and history of FHM." (PMID 33256119, 2020). "ATP1A2 and ATP1A3 have previously been implicated in familial hemiplegic migraine (OMIM 602481) and alternating hemiplegia (OMIM 614820)." (PMID 31572294, 2019).
familial hemiplegic migraine (continued). "Mutations of the genes encoding the Na/K-ATPase a-subunit (ATP1A2 and ATP1A3) have been described in three distinct human neurological disorders: familial hemiplegic migraine, rapid onset dystonia Parkinsonism, and alternating hemiplegia of childhood." (PMID 28593511, 2017). "The second type of familial hemiplegic migraine, FHM2 (FHM2; MIM602481), is caused by mutations in the gene ATP1A2 (ATP1A2; MIM182340)." (PMID 24403849, 2013). "Mutations in CACNA1A, ATP1A2 and SCN1A genes have been associated with familial hemiplegic migraine (FHM), a rare monogenic form of migraine." (PMID 23566281, 2013). "Mutations in three genes encoding neural ion channels, CACNA1A, ATP1A2, and SCN1A, have been described in patients with familial hemiplegic migraine (FHM), a rare monogenic, autosomal dominant form of migraine with aura." (PMID 21344296, 2011). "Both conditions share potential genetic underpinnings, with genes associated with familial hemiplegic migraine (such as CACNA1A, ATP1A2, and SCN1A) implicated in certain aura subtypes, though evidence for genetic influences is more robust in MA due to larger-scale studies." (PMID 40873917, 2025). "On the other hand, mutations in the four genes (CACNA-1A, ATP1A2, SCN1A, and PRRT2) identified in patients with familial hemiplegic migraine (FHM) are associated with a reduced threshold value of cortical spreading depression, which is also responsible for auras." (PMID 37048668, 2023). "Then, we briefly highlight key P-type ATPases involved in neuronal disorders such as the copper transporters ATP7A (Menkes disease), ATP7B (Wilson disease), the Na+/K+-ATPases ATP1A2 (familial hemiplegic migraine) and ATP1A3 (rapid-onset dystonia parkinsonism)." (PMID 24904274, 2014). "Genetic studies have identified several ion channel genes, including CACNA1A, ATP1A2, and SCN1A, which encode ion channels and transport proteins, as possible causes or contributors to familial hemiplegic migraine (FHM)." (PMID 38068897, 2023). "Familial hemiplegic migraine (FHM) is a severe neurogenetic disorder for which three causal genes, CACNA1A, SCN1A, and ATP1A2, have been implicated." (PMID 35928792, 2022). "Heritability seems to be more eminent in MwA subtype than MwoA, further supported by the identification of mutations in three ion transporter genes (CACNA1A, ATP1A2, and SCN1A) associated with familial hemiplegic migraine (FHM); a rare monogenic form of MwA." (PMID 36698892, 2022). "This is the case of PMM2-CDG and some channelopathies related to CACNA1A, ATP1A2, and SCN1A mutations, leading to episodes called familial hemiplegic migraine (FHM)." (PMID 34708008, 2021). "Indeed, one might reasonably screen the other familial hemiplegic migraine genes FHM2 (ATP1A2), FHM3 (SCN1A) along with FHM1 (CACNA1A) in case these are responsible for EA2‐like symptoms in a patient." (PMID 27066515, 2016). "An Italian family with familial hemiplegic migraine (FHM) with the absence of mutations in the known genes associated with this disorder, namely ATP1A2, ATP1A3, CACNA1A, and SCN1A, has recently been reported." (PMID 32549268, 2020). "Phenotypic-genotypic correlations, particularly mutations in the genes CACNA1A (P/Q-type voltage-gated Ca2+ channel), ATP1A2 (Na+-K+ ATPase), SCN1A (voltage-gated Na+ channel), are observed in familial hemiplegic migraine, as well as in generalized and focal epilepsies." (PMID 38405021, 2024). "In addition, 3 heterozygous missense mutations in other genes within the panel were identified (CACNA1A—p.Asp1723Asn and p.Ala987Ser; ATP1A2—p.Glu219Gln) suggesting that these patients have familial hemiplegic migraine (FHM) which has symptomatic features which overlap with CADASIL." (PMID 31915071, 2020). "Previous hypotheses of molecular mechanisms in migraine have come from familial hemiplegic migraine (FHM), a rare Mendelian form of the disease, where three ion channel genes are known to be involved (CACNA1A, ATP1A2, and SCN1A)." (PMID 27543003, 2016).
familial hemiplegic migraine (continued). "Familial hemiplegic migraine (FHM) is an autosomal dominant disorder, classified into 3 subtypes, based on the gene involved (CACNA1A in FHM1, ATP1A2 in FHM2 and SCN1A in FHM3)." (PMID 34320921, 2021). "The most established molecular knowledge of migraine comes from mutations in the three genes for familial hemiplegic migraine (FHM) – CACNA1A, ATP1A2 and SCN1A." (PMID 23675283, 2013).
hemiplegic migraine (34 papers, 2011 to 2025). "The fourth inherited AD variant was in ATP1A2 causing childhood-onset hemiplegic migraine, affecting also the proband’s sister, father, and two other relatives." (PMID 37563452, 2024). "Familial hemiplegic migraine type 2 (FHM2) is a condition associated with mutations in the ATP1A2 gene encoding the α2-isoform of the Na+,K+-ATPase." (PMID 37190017, 2023). "Most ATP1A2 mutations cause familial or sporadic hemiplegic migraine, some accompanied by ataxia, a range of epilepsies (from benign familial infantile convulsions to generalized epilepsy with febrile seizures plus) or intellectual disability." (PMID 34384358, 2021). "Mutations of ATP1A2 gene have been described in familiar hemiplegic migraine as dominant mutations, usually missense, which are thought to cause loss-of-function." (PMID 33711927, 2021). "Mutations in ATP1A2, the gene encoding the α2 subunit of Na+/K+-ATPase, are the main cause of familial hemiplegic migraine type 2 (FHM2)." (PMID 34384358, 2021). "The ATP1A2 coding α2 subunit of Na,K‐ATPase, which is predominantly located in astrocytes, is a causative gene of familial hemiplegic migraine type 2 (FHM2)." (PMID 32237043, 2020). "Another heterozygous gene mutation was identified in ATP1A2 in CAD-400 that is known to cause familial hemiplegic migraine type 2 (FHM2) (MIM#602481)." (PMID 31915071, 2020). "Both processes are essential for proper brain activity, and autosomal dominantly mutations in the ATP1A2 gene cause the neurological disorder Familial hemiplegic migraine type 2 (FHM2)." (PMID 27199775, 2016). "It is likely that in the future more mutations in the ATP1A2 gene will be found in sporadic hemiplegic migraine supporting the notion that it is a genetic disorder." (PMID 24396618, 2013). "We suggest that patients with sporadic hemiplegic migraine be tested for both ATP1A2 mutations which in some cases may be pathogenic, and prothrombin mutations which increase the stroke risk for this patient population." (PMID 24396618, 2013). "Mutations in CACNA1A, ATP1A2, and SCN1A, responsible for familial hemiplegic migraine types 1, 2, and 3 (FHM1, FHM2, and FHM3), are also linked to epilepsy." (PMID 40149800, 2025). "Genes coding for small conductance calcium-gated potassium channels (SKCa) such as KCNN3 have been associated with Familial Hemiplegic Migraine in some pedigrees, alongside the more well known CANCA1A and ATP1A2." (PMID 40823308, 2025). "There is a genetic basis for certain migraines, including hemiplegic migraine, which include mutations in genes like CACNA1A (calcium channel), ATP1A2 (Na/K-ATPase), and SCN1A (sodium channel)." (PMID 40149800, 2025). "This study presents a case report of a male adolescent diagnosed with familial hemiplegic migraine type 2 (FHM2), an autosomal dominant inheritance disorder caused by ATP1A2 mutation." (PMID 38379707, 2024). "Another study focused on hemiplegic migraine and found that patients with mutations in CACNA1A, ATP1A2, or SCN1A tended to have a lower age at disease onset." (PMID 37305749, 2023). "Hemiplegic migraine is a rare monogenic MA subtype caused by mutations in three main genes - CACNA1A, ATP1A2 and SCN1A - which encode ion channel and transport proteins." (PMID 31226929, 2019). "Up to now, four causative genes have been described in hemiplegic migraine (HM): CACNA1A on chromosome 19p13 (FHM1, MIM #301011), ATP1A2 at 1q23 (FHM2, MIM #182340), SCN1A at 2q24 (FHM3, MIM #182389) and, recently, PRRT2 at 16p11.2 (MIM #614386)." (PMID 24498617, 2013). "Recent evidence suggests a role for Atp1a2 in a mouse model of hemiplegic migraine (Cortical spreading depression)." (PMID 22675444, 2012). "Mutations in the ATP1A2 gene are responsible for Familial Hemiplegic type 2 (FHM2) or the sporadic hemiplegic migraine (SHM) counterpart if there is no family history of the disorder." (PMID 33882852, 2021). "Atp1a2+/− is a model mouse of familial hemiplegic migraine type 2." (PMID 32237043, 2020).
hemiplegic migraine (continued). "In conclusion, this work further strengthens the involvement of the ATP1A2 in hemiplegic migraine and highlights the importance to complement analysis of direct sequencing with quantitative gene analysis to exactly describe the association between ATP1A2 variations and hemiplegic migraine." (PMID 28593511, 2017). "Although the mutations in ATP1A2 that cause hemiplegic migraine are not as well-studied, it is thought that they may impair the transport of sodium and potassium ions and prolonging the presence of neurotransmitters between neurons." (PMID 28593511, 2017). "Mutations in CACNA1A, ATP1A2 and SCN1A genes are responsible for Familial hemiplegic migraine type 1 (FHM1), type 2 (FHM2), and type 3 (FHM3), respectively." (PMID 21731499, 2011).